CX3CR1 (C-X3-C motif chemokine receptor 1)
Diseases named in the same sentence as CX3CR1 in open-access papers (continued):
Sharing a sentence is not in itself a finding about the gene and the disease.
cardiovascular disease (24 papers, 2010 to 2026). "For example, hsa-miR-1276, a predicted regulator of CX3CR1, has been associated with the pathogenesis of cardiovascular diseases." (PMID 41007174, 2025). "Adhesion molecule CX3CR1 enables monocyte crawling along the endothelium and, therefore, is also associated with atherosclerotic plaque development, cardiovascular diseases, and the infiltration of macrophages into inflamed tissues." (PMID 38541021, 2024). "CX3CR1 is required for cellular transendothelial migration and entry into atherogenic plaques, which is associated with cardiovascular disease (CVD)." (PMID 32626718, 2020). "In the Framingham Heart Cohort study, CX3CR1 M-280 polymorphism was independently associated with a low risk of cardiovascular disease." (PMID 26688689, 2015). "Enhanced FKN and CX3CR1 expression have also been detected in rejected transplant biopsies and associated with cardiovascular disorders, renal inflammation and fibrosis." (PMID 22039526, 2011). "Previous research suggests that the target miRNA of CX3CR1, hsa-miR-1276, may be linked to the development of cardiovascular diseases." (PMID 41007174, 2025). "Our own published work strongly suggests that an accumulation of a CX3CR1+, senescent T cell compartment with short telomeres may contribute to higher mortality and age-related myocardial decline, and predispose towards cardiovascular diseases." (PMID 37510939, 2023). "This new understanding of CX3CR1+ cells in cardiovascular development and differentiation will help develop new strategies for disease investigation and regenerative therapy for cardiovascular disease." (PMID 40551012, 2025). "The CX3CL1/CX3CR1 axis mediates recruitment and extravasation of CX3CR1-expressing subsets of leukocytes and plays a pivotal role in the inflammation-driven pathology of cardiovascular disease." (PMID 33411754, 2021). "This study provides the fundamental role of CX3CR1-microglia, which can be used for treating cardiovascular disease because these receptors are involved in various pathological conditions." (PMID 32532282, 2020). "The CX3CL1/CX3CR1 axis is involved in leukocyte recruitment and in the development of cardiovascular disorders." (PMID 31109070, 2019). "In previous studies, the CX3CL1/CX3CR1 system has been shown to be involved in the pathophysiology of cardiovascular disorders including heart failure and inflammatory cardiomyopathy." (PMID 28800592, 2017). "However, further prospective and interventional studies are needed to evaluate the impact of the CX3CL1/CX3CR1 axis and the impact of sex on the pathogenesis of cardiovascular diseases in affected populations." (PMID 41153665, 2025). "One contributing factor to the burden of cardiovascular disease in CKD is a chronic micro-inflammatory state which may include systemic activation of the CX3CL1- CX3CR1 axis." (PMID 34163473, 2021). "In addition, angiotensin II (Ang II) dysregulation was determined in many cardiovascular diseases, and it could upregulate CX3CR1 expression in VSMCs via the NADPH oxidase/ROS/p38 MAPK pathway." (PMID 33531038, 2021).
neurological diseases (20 papers, 2013 to 2025). "CX3CR1 has been implicated in both neuroprotective and detrimental effects by regulating inflammation in neurological disorders." (PMID 41223260, 2025). "Fractalkine/CX3CR1 signalling has been implicated in many neurodegenerative and neurological diseases of the central nervous system (CNS)." (PMID 28810923, 2017). "The broader role of CX3CL1/CX3CR1 signaling in the crosstalk between neurons and glial cells in CNS structures of various neurological diseases was reviewed." (PMID 38892268, 2024). "CX3CL1/CX3CR1 signal has been extensively researched on as an important mediator of inflammatory responses in neurological diseases." (PMID 37234914, 2023). "Recently, the signaling pathway mediated by fractalkine CX3CL1 and its receptor CX3CR1 has received considerable attention as an important mediator of inflammatory responses in several neurological disorders." (PMID 33065974, 2020). "Increasing evidence has indicated that the chemokine CX3CL1 and its receptor, CX3CR1, play important roles in modulating the inflammatory response in PD and in other neurological disorders." (PMID 33065974, 2020). "In summary, emerging evidence suggests that the CX3CL1/CX3CR1 axis is an attractive potential therapeutic target due to its ability to control inflammation in the neurological disorders." (PMID 33065974, 2020). "CX3CL1/CX3CR1 signaling modulates microglia activation, and depending upon the type and time of injury, either protects or exacerbates neurological diseases." (PMID 26329692, 2015). "In addition, the use of human samples has demonstrated that alterations in CX3CL1 and CX3CR1 expression and synthesis are quantifiable indicators of the progression of certain neurological diseases." (PMID 39940727, 2025). "In conclusion, F4/80 and CX3CR1-expressing macrophages play important regulatory roles in neuroinflammation, which polarizes to the Arg1+ M2 phenotype, contributing to the treatment of neurological disorders." (PMID 36814909, 2023). "However, the proportions of CX3CR1−/− mice showing neurological disorder were similar to those of CX3CR1+/+ mice following intranasal and intraperitoneal inoculation with JEV." (PMID 31316515, 2019). "In support of this finding, the CX3CR1−/− mice showed a rapid and higher proportion of neurological disorders starting at 4–5 dpi, compared to CX3CR1+/+ mice that displayed the delayed signs of neurological disorder around 6–7 days after footpad inoculation of JEV." (PMID 31316515, 2019). "Discrepancies in various reports on the neuroprotective versus neurodegenerative functions of neuronal CX3CR1 might be attributed to the regional specificity of its expression in different neurological disorders." (PMID 29323156, 2018). "To shed light on this issue, we studied the mRNA expression of CD200 and CX3CR1 (also known as fractalkine receptors), which have been associated with inhibitory actions on brain microglia, and MCP-1, a potent chemokine which has been implicated in different neurological disorders." (PMID 24565378, 2014). "In addition, CX3CR1 is a chemokine receptor expressed in microglia, as well as the mononuclear phagocyte system, it is unclear whether Tgm2 knockout in macrophages, monocytes or neutrophils will contribute to the pathogenesis of neurological diseases." (PMID 36878712, 2023). "CX3CR1+ microglia perform different activations to change mitochondrial dynamics and switch between OXPHOS and glycolysis, which directly affects neurological disorders." (PMID 36814909, 2023). "Microglia from non-neurological disease controls and individuals with ASD in both the snRNA-seq and scRNA-seq datasets expressed characteristic microglial markers such as P2RY12, CX3CR1, AIF1, CSF1R and IL18." (PMID 35739273, 2022).
renal diseases (20 papers, 2009 to 2026). "In the development of kidney diseases, the chemotaxis and adhesion of immune cells are facilitated by CX3CR1 and its highly selective ligand CX3CL1." (PMID 38951833, 2024). "CX3CR1 is crucial in the progression of IgA nephritis, nephrotoxic nephritis, renal candidiasis and other renal diseases." (PMID 38390317, 2024). "The idea that Cx3cr1 promotes kidney disease is supported by studies from a hypertensive mouse model showing reduced macrophage infiltration and interstitial fibrosis in Cx3cr1 deficient kidneys compared to control kidneys." (PMID 37256130, 2023). "Collectively, these data indicate that Cx3cr1 regulates macrophage and dendritic cell accumulation in the adult kidney; however, the role of Cx3cr1-dependent phagocytes in kidney disease is still controversial." (PMID 37256130, 2023). "In previous studies, the overexpression of CX3CL1 and CX3CR1+ cells was related to renal disease with protective effects of macrophage depletion blocking CX3CR1 in an experimental study." (PMID 33986961, 2021). "Among other highly inflammatory forms of kidney disease, interstitial CX3CR1+ positivity correlated with outcome in human transplant rejection." (PMID 34009468, 2021). "The chemokine CX3CL1 (fractalkine) and its receptor CX3CR1 are exemplary in this regard as they are highly expressed and further upregulated in a range of kidney diseases." (PMID 34009468, 2021). "further studied the expression of CX3CR1 by infiltrating cells in human kidney disease using similar control samples." (PMID 34163473, 2021). "The consequence of this overlap is well illustrated by two recent studies examining how CX3CR1 affects renal disease: both studies agreed that mononuclear phagocytes are substantially reduced in the kidneys of CX3CR1-deficient mice." (PMID 26388867, 2015). "CX3CR1 has been reported to regulate immune responses such as inflammation, cell adhesion, and chemotaxis, and therefore plays a crucial role in the progression of kidney diseases such as IgA nephritis, nephrotoxic nephritis, and renal candidiasis." (PMID 38390317, 2024). "On the other hand, the CX3CL1/CX3CR1 axis may play a protective role against some kidney disorders." (PMID 33986961, 2021). "CX3CR1/CX3CL1 mediates a mechanism of leukocyte capture, firm adhesion, and activation which is independent of that induced by integrins and has been implicated in the pathophysiology of several inflammatory diseases, including renal diseases, allograft rejection, and atherogenesis." (PMID 19587779, 2009). "This concise review summarizes the current knowledge and recent developments regarding CX3CR1 and CX3CL1 expressing cell types and their role of in kidney disease." (PMID 34009468, 2021).
inflammation (9 papers, 2011 to 2024). Aberrant reaction of the microcirculation characterized by movement of fluid and leukocytes from the blood into extravascular tissues. "Cell culture and mouse studies suggest that the G protein mimics the cytokine CX3CL1 by binding to CX3CR1 on immune cells, which is thought to cause increased pulmonary inflammation in vivo." (PMID 33600439, 2021). "Pulmonary inflammation was significantly enhanced in the CX3CR1−/− animals compared to the C57BL/6J animals, as assessed by microvascular permeability, polymorphonuclear neutrophil (PMN) migration into lung tissue and alveolar space." (PMID 33791319, 2021). "In our model of acute pulmonary inflammation, we also detected increased chemokine levels in the CX3CR1−/− mice based on stronger activation of the AKT, ERK1/2, and NFκB signaling cascades." (PMID 33791319, 2021). "Further, our data suggests that interruption of the CX3CR1/fractalkine pathway could be a potential therapeutic target to reduce the survival of S1-containing non-classical monocytes and the associated vascular inflammation previously discussed." (PMID 35082777, 2021). "In a murine model of LPS-induced acute pulmonary inflammation, we investigated the role of the chemokine CX3CL1 and its receptor, CX3CR1." (PMID 33791319, 2021).
bacterial infection (7 papers, 2015 to 2024). "Frequencies of pHrodo red+ cells, which only emit a fluorescent signal in acidic environments, were significantly increased in CX3CR1+ Cre+ phagocytes compared to Cre- controls 6 hours after bacterial infection." (PMID 39178311, 2024). "It is likely that these cells and the expression of CX3CR1 will be important for survival from other intracellular bacterial infections and future studies should seek to examine this." (PMID 31032897, 2019). "In contrast, CX3CR1-mediated signalling is demonstrated to be essential for macrophages in mounting defence against bacterial infection." (PMID 27549131, 2016). "We identify CX3CR1 as the marker that differentiates memory CD8+ T cells with direct cytotoxic effector function generated in response to viral or bacterial infections." (PMID 26404698, 2015). "Although the CX3CR1 driver may also target NK cells and dendritic cells in the contact of acute bacterial infection, the primary drivers of response are macrophages and neutrophils." (PMID 34464475, 2021). "As GFP (CX3CR1) expression separates memory CD8+ T cells into two populations, we addressed the question whether antigen-specific GFP+ (CX3CR1+) and GFPneg (CX3CR1neg) memory CD8+ T cells generated after viral or bacterial infections in CX3CR1+/GFP reporter mice had distinct functional properties." (PMID 26404698, 2015). "To directly test the proliferative capacity of GFP+ (CX3CR1+) versus GFPneg (CX3CR1neg) memory CD8+ T cells in vivo, we adoptively transferred both populations and analysed their numbers after viral or bacterial infections." (PMID 26404698, 2015). "Sixty days after viral or bacterial infection, GFP+ (CX3CR1+) CD62LhiCD8+ T cells constituted about 20–40% of antigen-specific memory CD8+ T cells in lymph nodes." (PMID 26404698, 2015). "Indeed, CX3CR1+ memory CD8+ T cells were found in lymph nodes more than 60 days after viral and bacterial infection." (PMID 26404698, 2015).
immune diseases (6 papers, 2016 to 2025). "In addition, as no specific immune function tests were performed, we cannot definitively prove that decreased CX3CR1 mRNA is associated with immune dysfunction in ICU patients." (PMID 27364780, 2016).
brain disease (5 papers, 2013 to 2020). "This mouse line, has since contributed enormously to our current understanding of microglia biology, and CX3CR1-deficient homozygotes have been used extensively to study the role of CX3CR1 in various models of brain disease." (PMID 23734099, 2013). "Although there is a growing body of literature, which is supported by extensive studies on the role of the CX3CL1/CX3CR1 signaling pathway in brain diseases, the published results are relatively controversial." (PMID 33065974, 2020). "During the last decade, there has been a growing interest in the roles that the CX3CL1/CX3CR1 signaling pathway plays in the neuropathology of a diverse array of brain disorders." (PMID 33065974, 2020). "This receptor is highly expressed in microglia and CX3CR1-GFP knock-in mice (where GFP replaced one CX3CR1 allele) have been used to specifically study, in vivo, the role of microglia in AD and other brain diseases." (PMID 30158892, 2018). "Nevertheless in each case insights about upstream and downstream signaling from CX3CR1/CX3CL1 have been informative and may point to new therapeutic directions for brain disease." (PMID 25152714, 2014).
infectious disease (4 papers, 2012 to 2023). A disorder directly resulting from the presence and activity of a microbial, viral, or parasitic agent in humans. "Previous reports demonstrated that CD14lowCD16+ monocytes expressed higher levels of CX3CR1 (a fractalkine receptor) and HLA-DR, proinflammatory cytokines and higher potency in antigen presentation in human inflammatory and infectious diseases." (PMID 22335964, 2012).
psychiatric diseases (4 papers, 2015 to 2021). "From this point of view and independently of fractalkine/CX3CR1 signaling, it is worth noting that dysfunction of microglial cells is increasingly suspected to occur in psychiatric diseases associated with neurodevelopmental disorders." (PMID 26347402, 2015). "Therefore, CX3CR1-deficient mice have been extensively employed to explore the roles of microglia in various psychiatric diseases." (PMID 34683104, 2021). "Furthermore, compared with WTs, CX3CR1-deficient mice were resistant to stress, implicating an intriguing detrimental role of CX3CR1 in eliciting susceptibility to psychiatric disorders." (PMID 31772305, 2020).
cerebral artery (3 papers, 2014 to 2025). "Targeting CX3CR1 on PMN-MDSCs could serve as a potential therapeutic strategy to prevent stomach carcinogenesis." (PMID 41280721, 2025). "This study reported the importance of CX3CL1 acting for transmigration of CX3CR1-positive non-classical monocytes from the blood into the human fibrotic lung in different DPLDs (HP, CTD-ILD and non-specific interstitial pneumonia)." (PMID 34208027, 2021).
peripheral neuropathy (3 papers, 2021 to 2024). A disorder affecting the peripheral nervous system. "CX3CR1 is expressed in the dorsal horn of the spinal cord and mediates neuron–glia communication; in the case of peripheral neuropathy with interruption of homeostasis, it increases signaling in the dorsal horn of the spinal cord, thus increasing maladaptive neuron–glia signaling." (PMID 38998053, 2024).
central nervous system diseases (2 papers, 2022). "A considerable amount of literatures shows that FKN/CX3CR1 signalling pathway, as an entry point of interaction between neurons and microglia, plays an important role in central nervous system diseases by modulating/inhibiting microglia activation." (PMID 35023309, 2022). "Fractalkine (FKN)/CX3CR1 is reported to regulate microglia activation in central nervous system diseases." (PMID 35023309, 2022). "A tight‐knit relationship between FKN/CX3CR1 signalling pathway and the complex network of neurons and glia has been reported in the central nervous system diseases, ocular diseases and other organ diseases." (PMID 35023309, 2022).
metabolic disease (2 papers, 2017 to 2018). A congenital disorder (due to inherited enzyme abnormality) or acquired (due to failure of a metabolically important organ) disorder resulting from an abnormal metabolic process. "These translational strategies hold promise for future studies targeting the CX3CL1/CX3CR1 axis to treat inflammation associated with metabolic diseases." (PMID 28396851, 2017). "Recent study found that sex differences in microglial activation exist in themodulation of energy homeostasis and identified CX3CR1 signaling as a potential therapeutictarget for the treatment of metabolic diseases in mice such as obesity." (PMID 29692197, 2018).
adenocarcinoma (1 paper, 2019). A common cancer characterized by the presence of malignant glandular cells. "The expressions of CX3CR1 and HIF-1α were particularly high in adenocarcinomas of stages II and III, compared to normal OvCa tissues." (PMID 31077234, 2019). "Tissue microarrays of human OvCa showed elevated expression of CX3CR1 and HIF-1α compared to normal cells, and their levels were higher in adenocarcinoma stages II and III." (PMID 31077234, 2019). "Our results showed that, among adenocarcinomas, stage III had higher expressions of CX3CR1 in the membrane and cytoplasm." (PMID 31077234, 2019).
osteoarthropathy (1 paper, 2022). "CX3CR1 regulates the Wnt/β-catenin signaling, which consequently regulates the proliferation of chondrocytes and apoptosis in osteoarthropathy." (PMID 35996406, 2022).
CX3CR1 also shares sentences with these, for which no sentence is quoted: acute myocardial infarction (6 papers); kidney damage (4); Parkinson’s (4); retinitis pigmentosa (4); retinopathy (4); candidiasis (3); dementia (3); Hypercholesterolemia (3); idiopathic pulmonary fibrosis (3); neurodevelopmental disorder (3); acute kidney injury (2); allergies (2); Atrophy (2); chronic pancreatitis (2); end-stage renal disease (2); Headache (2); HIV-associated dementia (2); intestinal inflammation (2); kidney failure (2); Listeria infection (2); oral squamous cell carcinoma (2); Peritoneal Fibrosis (2); viral diseases (2); acute myeloid leukemia (1); acute myocarditis (1); acute respiratory distress syndrome (1); adenopathy (1); allergic asthma (1); ankylosing spondylitis (1); Aortic dissection (1).
A further 82 diseases each share a sentence with CX3CR1 in 1 paper.